ZNF12 (zinc finger protein 12)
Description:
Transcriptional repressor which suppresses activation protein 1 (AP-1)- and serum response element (SRE)-mediated transcriptional activity.
Synonyms: GIOT-3; KOX3; ZNF325; HZF11
Tractability: PROTAC: UniProt records ubiquitination sites on it; ubiquitination databases record sites on it.
Gene: Protein-coding gene on chromosome 7 (6,688,433 to 6,706,947, reverse strand). Ensembl gene ENSG00000164631.
Subcellular location: Nucleus
Subcellular location (Human Protein Atlas): Nucleoplasm; Centrosome
Pathways (Reactome):
Gene expression (Transcription): Generic Transcription Pathway
Gene Ontology:
Molecular function: protein binding; sequence-specific double-stranded DNA binding; DNA-binding transcription factor activity, RNA polymerase II-specific; RNA polymerase II cis-regulatory region sequence-specific DNA binding
Biological process: negative regulation of DNA-templated transcription; regulation of transcription by RNA polymerase II; regulation of DNA-templated transcription
Cellular component: nucleoplasm; nucleus
Genetic constraint (gnomAD): Loss-of-function variants: 34 observed, 69.27 expected, observed/expected ratio (o/e) 0.49, 90% interval 0.37 to 0.65. The upper end of that interval is the gene's LOEUF score, 0.65, which puts it in group 2 of 6, group 1 being the genes least tolerant of losing a copy. Missense variants: 697 observed, 867.81 expected, observed/expected ratio (o/e) 0.8, 90% interval 0.75 to 0.86. Synonymous variants: 320 observed, 293.45 expected, observed/expected ratio (o/e) 1.09, 90% interval 0.99 to 1.2.
Homologues: Orthologues: chimpanzee ZNF12 (99% identical), macaque ZNF12 (98% identical), pig ZNF12 (91% identical), dog ZNF12 (91% identical), chimpanzee ZNF12 (89% identical), rabbit ZNF12 (85% identical), guinea pig ZNF12 (82% identical), rat Zfp12 (81% identical), mouse Zfp12 (80% identical). Paralogues in human: RBAK (71% identical), ZNF658 (45% identical), ZNF33B (43% identical), ZNF717 (41% identical), ZNF484 (40% identical), ZNF182 (40% identical), ZNF41 (40% identical), ZNF568 (40% identical), ZNF334 (39% identical), ZNF605 (39% identical), ZNF28 (39% identical), ZNF33A (39% identical), and 164 more.
Diseases named in the same sentence as ZNF12 in open-access papers:
ZNF12 is named in the same sentence as 6 diseases in open-access papers, as found by Europe PMC text mining. Sharing a sentence is not in itself a finding about the gene and the disease. The quoted sentences say what the papers report.
glioma (1 paper, 2024). A benign or malignant brain and spinal cord tumor that arises from glial cells (astrocytes, oligodendrocytes, ependymal cells). "Currently, no data are available on therole played by the DDX18, ZNF12, andCRISPLD1 genes in patients with gliomas and low-grade gliomasin particular." (PMID 39539523, 2024).
Hypertension (1 paper, 2024). The presence of chronic increased pressure in the systemic arterial system. "Similarly, ZNF12, the regulator of ATP5J as well as COX6C, was also identified as hypertension-associated QTL in rats." (PMID 38410507, 2024).
ZNF12 also shares sentences with these, for which no sentence is quoted: cancer (1 paper); diabetes (1); pancreatic adenocarcinoma (1); tumor (1).